CFTR (CF transmembrane conductance regulator)
Diseases named in the same sentence as CFTR in open-access papers (continued):
Sharing a sentence is not in itself a finding about the gene and the disease.
male infertility (70 papers, 2010 to 2026). The inability of the male to effect fertilization of an ovum after a specified period of unprotected intercourse. "Congenital absence of the vas deferens (CAVD) is a major cause of obstructive azoospermia and male infertility, with its genetic etiology primarily associated with CFTR (autosomal recessive) and ADGRG2 (X-linked) mutations." (PMID 42199298, 2026). "Understanding the genetic architecture of CFTR mutations including their classification, inheritance patterns, and genotype–phenotype correlations is essential for diagnosing CF-related male infertility." (PMID 41009940, 2025). "Male infertility in CF is primarily due to anatomical obstruction of the reproductive tract caused by CFTR dysfunction during development." (PMID 41009940, 2025). "Particularly relevant to this with regards to male infertility are the c.[1210-34TG[m];1210-12T[n]] polymorphisms of the poly-thymine (poly-T) tract and its modulating TG repeats in intron 8 of CFTR, which are a mandatory search in CBAVD cases." (PMID 39062716, 2024). "Predictably, in this subset of patients, the identification of CFTR variants associated with CFTR-RD limited to male infertility is considerably more frequent than in the general population." (PMID 39062716, 2024). "Mutations and polymorphisms in the CFTR gene, such as (TG)m and Tn polymorphic loci in intron 8 at the splice acceptor site of exon 9, can also contribute to male infertility." (PMID 38611676, 2024). "We identified novel compound heterozygous CFTR mutations in two brothers and summarized the literature regarding CFTR mutation and male infertility." (PMID 37489040, 2023). "In conclusion, this work provided the first insight into monogenic causes of male infertility in Jordan and highlighted a different spectrum of genotype-phenotype correlation of known pathogenic CFTR variants in the Jordanian population." (PMID 34190021, 2022). "Although the genetic correlation between CFTR gene mutations and CBAVD-induced male infertility has been well studied, it has recently been established that CFTR gene mutations are involved in other forms of male infertility in addition to the CBAVD phenotype." (PMID 35646184, 2022). "The frequencies of the most common genetic abnormalities associated with male infertility are as follows: chromosomal abnormalities 5–7%, Y-chromosome deletions 5–10%, CFTR gene mutations 5%, AR mutations 2–3%." (PMID 34290736, 2021). "CFTR-related CBAVD are the most well-known forms of CAVD because of their involvement in male infertility and their association with CF-causing mutations." (PMID 32025909, 2021). "Chromosomal alterations, inversions, translocations, Y chromosome microdeletions, and gene mutations (for example single-nucleotide variants (SNVs) in CFTR) are the main genetic variants causing male infertility." (PMID 29779145, 2018). "For male infertility, the panel includes Y chromosome microdeletions, CFTR mutations, and sex chromosome aneuploidies." (PMID 29779145, 2018). "The genetic link between CFTR mutations and a genital form of male infertility (CBAVD) is well established." (PMID 28042420, 2017). "The genetic association between CFTR mutations and male infertility due to CBAVD is well established." (PMID 28042420, 2017). "Several studies have revealed involvement of CFTR mutations in other forms of male infertility due to defective spermatogenesis." (PMID 28042420, 2017). "At the genic level, male infertility has been linked with protamine gene mutations, 5-alpha reductase deficiency, androgen receptor gene mutations and cystic fibrosis transmembrane conductance regulator gene (CFTR) mutations." (PMID 28042420, 2017). "The association between some of these CFTR mutations and male infertility have already been detected like ΔF508, M470V, ΔI507, N1303K." (PMID 25246892, 2012).
male infertility (continued). "It has been shown that mutations in the genes associated with ABC transporters, such as Abcc4 and CFTR, in the epididymis may interfere with male infertility through the malformation of the epididymis." (PMID 39997926, 2025). "No fertile controls displayed the CFTR mutation while 6 of 16 oligozoospermic and 10 of 15 azoospermic patients did, suggesting that CFTR may be associated with male infertility (oligozoospermia and azoospermia)." (PMID 37895049, 2023). "Pathogenic variants in the CFTR gene have been associated with different forms of male infertility." (PMID 34190021, 2022). "Finally, it is highly relevant in terms of our understanding of CF pathology and how this disease causes male infertility to revisit the cells that express CFTR in the epididymis." (PMID 32855272, 2020). "Genetic variants of the CFTR gene are a relatively frequent cause of male infertility, due to obstructive azoospermia, or in atypical forms of CF such as the congenital absence of the vas deferens, bilateral ejaculatory duct obstruction, or bilateral obstructions." (PMID 33574797, 2020). "CFTR, mutations of which are associated with male infertility, might be coregulated by FXR1, HNRNPA1, MATR3, PABPC1, G3BP2, FMR1, and SRSF7." (PMID 32316190, 2020). "Therefore, a specific agonist of AGTR2 should be considered for the development of therapeutic methods to treat male infertility caused by impaired ADGRG2-Gq-CFTR signaling, such as that observed in CF patients." (PMID 29393851, 2018). "Some homozygous or heterozygous CFTR mutations only manifest as male infertility." (PMID 29079751, 2017). "CFTR variants in subjects with chronic rhinosinusitis or male infertility (age >30 years)." (PMID 25033378, 2014). "Indeed, CFTR mutations are a leading cause of male infertility and defective ATP signaling in the epididymis might contribute to post-testicular tract dysfunction." (PMID 40128095, 2025). "Besides, CFTR in sperm may be involved in the transport of HCO3−, which is important for sperm capacitation, and CFTR mutations with impaired CFTR function may lead to reduced sperm fertilizing capacity and male infertility." (PMID 29930176, 2018). "Current diagnostic guidelines endorse three principal genetic evaluations as standard practice in male infertility assessment: KA for chromosomal architecture; Y-chromosomal microdeletion screening for AZF region integrity; and CFTR gene mutational analysis." (PMID 40951413, 2025). "A team from Lille (Inserm U16-Biochemistry of Normal and Pathological Proteins, France) was the first to raise the question of CFTR gene responsibility in the most common form of male infertility." (PMID 39273547, 2024). "Reduced or absent CFTR activity leads to increased viscosity of epididymal fluid and male infertility." (PMID 38611676, 2024). "Autosomal genes, e.g., the CFTR gene (located on chromosome 7) and the FSH receptor (FSHR) gene (located on chromosome 2), have been shown to cause male infertility." (PMID 37174664, 2023). "The SPATA16, CFTR, KIF6, STPG2, and DRC7 mutations are associated with male infertility, specifically azoospermia, and a further examination of this genetic function is required." (PMID 37895049, 2023). "There are also male infertility cases caused by defects in single genes including CFTR, DDX3Y, SYCP3, TEX11, AURKC, and DPY19L2, but the number of genes confidently linked to male infertility remains very low." (PMID 34190021, 2022). "Over the years, the IVS8 c.1210-12T[5_9] (polypyrimidine tract in intron 8) and adjacent c.1210-35_1210-12GT[8_13] (TG repeat tracts) in the CFTR gene have received much more attention due to their potential roles in the development of male infertility." (PMID 38624701, 2021). "Currently, male infertility’s genetic diagnostic workup, restricted to the karyotype, AZF region, and CFTR gene, is considered ineffective." (PMID 34201025, 2021).
male infertility (continued). "Currently, the main genetic tests routinely used for the diagnosis of male infertility are the karyotype, the study of chromosome Y microdeletions, and the analysis of the CFTR gene." (PMID 31412890, 2019). "Thus, large-scale cohort studies as well as examination of entire gene or the high number of CFTR mutations may be necessary to substantiate the hypothesis of a putative link between a particular combination of CFTR mutations and polymorphisms and other types of male infertility." (PMID 29986553, 2019). "Whereas the impact of CFTR defects on male infertility has been extensively studied, the effects of SLC26A3 variants on male infertility without CLD remain poorly understood." (PMID 29079751, 2017). "Several human genes are known with mutations causing male infertility (AR; AZF gene families; CFTR, DM-1, DNAH gene family, FGFR1, FSHR, INSL3, KAL-1, LGR8-GREAT, LHR, POLG)." (PMID 26097523, 2015). "Congenital bilateral absence of vas deferens (CBAVD) is the most common CFTR-related disorder (CFTR-RD) that explains about 1–2% of the male infertility cases." (PMID 25386751, 2014). "Thus, understanding CFTR genetics is crucial not only for diagnosing CF in the typical context, but also for recognizing atypical and less obvious manifestations of CFTR dysfunction such as isolated male infertility." (PMID 41009940, 2025). "In this study, an Ampiseq targeted NGS panel and Illumina TruSeq WES were both used to pinpoint six specific genes (KIF6, DRC7, STPG2, SPATA16, CFTR, CMTM2) that play a role in MT association and spermiogenesis, which are crucial factors in understanding the causes of male infertility." (PMID 37895049, 2023). "CBAVD represents 3% of male infertility and is the most frequent CFTR-related disorder (CFTR-RD)." (PMID 37445855, 2023). "NHE3 and CFTR are known to interact in various cellular contexts, and therefore it is thought that the NHE3 KO phenotype is at least partially due to the loss of CFTR activity, as CFTR KO mice also display a similar male infertility phenotype." (PMID 37834431, 2023). "A recent methodological evolution which tends to be generalized is not to use in the first approach CFTR mutation-targeted tests but to directly offer a comprehensive scanning by NGS methodology of a panel of genes including CFTR, ADGRG2 and other genes linked to male infertility." (PMID 32025909, 2021). "Two rare CFTR likely benign variants were identified in family members, but they did not segregate with the male infertility phenotype." (PMID 30389958, 2018). "The genetic association between cystic fibrosis transmembrane conductance regulator(CFTR) gene mutations and male infertility due to congenital bilateral absence of vasdeferens (CBAVD) is well established." (PMID 28042420, 2017). "Either one or two CFTR mutations appear in approximately 80% of the CBAVD cases without CF, and non-CBAVD related male infertility with reduced sperm quality is associated with homozygosity or heterozygosity for less-pathogenic CFTR mutations." (PMID 29079751, 2017). "Clearly, understanding the mutation profiles in CF patients could contribute to the further design of drugs targeting CFTR in male infertility." (PMID 27483469, 2016). "Future studies might be warranted to explore the possible role of ClC-5 in male infertility and to determine testicular function in Dent disease 1 patients, analogous to the role of the CFTR gene in male infertility." (PMID 25001568, 2014). "CFTR-RDs represent a partial CFTR dysfunction and include conditions such as chronic sinusitis, idiopathic recurrent pancreatitis, and isolated congenital absence of the vas deferens (a cause of male infertility) without significant lung or pancreatic disease." (PMID 41009940, 2025).
male infertility (continued). "Based on the present case-control study, the CFTR gene mutations and IVS8-Tn polymorphisms are correlated with CBAVD; however, extensive investigations are necessary to determine the exact relationship between the gene mutations and other forms of male infertility." (PMID 29986553, 2019). "Therefore, manipulation of the signaling components of the ADGRG2-Gq/β-arrestin-1/CFTR complex by small molecules may be an effective therapeutic strategy for male infertility." (PMID 29393851, 2018). "Therefore, larger studies of CFTR mutation screening among unselected infertile males with different sperm counts may contribute to the elucidation of the role of CFTR gene in the impaired spermatogenesis and male infertility." (PMID 25386751, 2014). "There was no increased risk of male infertility in cases without CFTR variants (p = 0.28), but there was significant risk in cases with either CFTRBD or CFTRCF alleles (p = 0.023; OR 10.7; CI 1.03–536) or as a recessive genotype (p = 1.2×10−7; OR 303; CI 23–15783)." (PMID 25033378, 2014). "Although little is known about the role of the cystic fibrosis transmembrane regulator (CFTR) gene in reproductive physiology, numerous variants in this gene have been implicated in etiology of male infertility due to congenital bilateral absence of the vas deferens (CBAVD)." (PMID 20532200, 2010). "The importance of both CFTR and SLC26A3 functions in the physiology of male fertility is supported by their molecular interaction, by the male infertility phenotypes of CF and CLD, and by their role in rodent sperm motility and capacitation." (PMID 29079751, 2017). "Further studies on members of the SLC26 family are likely to provide important data on the pathogenesis of male infertility and the action of the SLC26A3/CFTR complex in sperm cells." (PMID 29079751, 2017). "Notably, CFTR variants are also associated with male infertility without CF." (PMID 29079751, 2017). "Most SNP-populated genes related to male infertility include HLA-DQB1 (20 SNPs), HLA-DRB1 (15 SNPs), MTHFR (10 SNPs), BRCA2 (9 SNPs), ACE (8 SNPs), CFTR (6 SNPs), CDH1 (6 SNPs), SRD5A2 (6 SNPs), HLA-DQA1 (5 SNPs) and MMP9 (5 SNPs)." (PMID 29263816, 2016). "If the CAVD man has no mutation after comprehensive CFTR testing and normal renal imaging, an ADGRG2 analysis should be suggested, especially if there is a family history of male infertility." (PMID 32025909, 2021). "CFTR-RDs principally include isolated male infertility by congenital bilateral absence of the vas deferens, idiopathic pancreatitis, disseminated bronchiectasis and chronic rhinosinusitis." (PMID 32512765, 2020). "Studies have revealed a strong association between mutations of CFTR gene and the congenital bilateral absence of the vas deferens (CBAVD), but the role of this gene in other types of male infertility is still unclear." (PMID 29986553, 2019). "However, the molecular mechanisms behind male infertility are still not fully understood, and other genetic factors, such as methylenetetrahydrofolate reductase (MTHFR) and cystic fibrosis transmembrane conductance regulator (CFTR), have also been reported as contributors." (PMID 40843731, 2025). "Thus, screening of CFTR mutations is proposed for all infertile men with CBAVD, however, the association of CFTR mutations and non-CBAVD male infertility, is uncertain." (PMID 28042420, 2017). "Mutant CFTR, however may also be involved inthe etiology of male infertility in non-CBAVD cases." (PMID 28042420, 2017). "The contribution of CFTR variants however varies from one condition to another, and may act in a multifactorial context, with other genes being potentially involved, such as ADGRG2 in male infertility by the absence of vas deferens or PRSS1, SPINK1 and CTRC in pancreatitis." (PMID 32512765, 2020).
male infertility (continued). "Indeed, milder phenotypes of CF, such as male infertility without other manifestations, are associated with normal Cl− channel activity but with aberrant HCO3− secretion only, giving support to the crucial role of the interaction between SLC26 transporters and CFTR." (PMID 29079751, 2017).
chronic pancreatitis (64 papers, 2007 to 2026). A chronic inflammatory process causing damage and fibrosis of the pancreatic parenchyma. "Although the overall impact of CFTR variants on chronic pancreatitis (CP) risk is more modest than earlier thought, recent large-scale cohort studies have confirmed that CFTR mutations can still play a pathogenic role." (PMID 41510163, 2026). "Our patient had various possible etiologies for the development of chronic pancreatitis: tobacco, genetic mutation of CFTR, and recurrent acute pancreatitis." (PMID 39996177, 2025). "They found that PD has a 47% frequency in patients with CFTR gene mutations as if these entities are cofactors associated with acute or chronic pancreatitis." (PMID 38978842, 2024). "Studies have shown that patients presenting with idiopathic recurrent or chronic pancreatitis have an increased frequency of cystic fibrosis transmembrane conductance regulator (CFTR) gene mutations." (PMID 36832409, 2023). "Patients presenting with recurrent-acute or chronic pancreatitis have an increased frequency of mutations in the CFTR gene." (PMID 36832409, 2023). "Inherited risk factors include gene variants damaging in PRSS1 and CFTR (both also associated with chronic pancreatitis), and tumor suppressors involved in DNA repair processes (including BRCA1, BRCA2, PALB2, MLH1, CDKN2A, and ATM)." (PMID 37452870, 2023). "There are also genetic (including hereditary chronic pancreatitis due to mutation of the PRSS1 gene but also other forms due to mutations of other genes such as CFTR, SPINK1, TRPV6, and CTRC) and idiopathic forms." (PMID 36765725, 2023). "We already mentioned in the introduction that an early onset (hereditary) chronic pancreatitis, which can also be caused by a mutation of the CFTR channel, leads to an increased risk to develop PDAC." (PMID 33841132, 2020). "Rare pathogenic variants in the SPINK1, PRSS1, CTRC, and CFTR genes have been strongly associated with a risk of developing chronic pancreatitis (CP)." (PMID 30420730, 2018). "First, to identify candidate CFTRBD variants, we conducted a systematic review of the literature to compile CFTR variants that have been reported at least twice in previous chronic pancreatitis case-control genetic studies, plus common CFTRCF variants." (PMID 25033378, 2014). "In this article, we propose that the cytoplasmic mislocalization of the CFTR in pancreatic duct cells is a cause of pancreatic stone formation in chronic pancreatitis." (PMID 23133422, 2012). "We have shown that the mislocalization of the CFTR in the cytoplasm of pancreatic ducts is a possible cause of the low HCO3- concentration found in pancreatic juice in chronic pancreatitis." (PMID 23133422, 2012). "In conclusion, the PRSS1 mutations appear capable of inducing chronic pancreatitis whereas CFTR and SPINK-1 seem to be “gene modifiers” capable of inducing the disease in the presence of a risk factor such as alcohol." (PMID 20049222, 2009). "We studied mutations of CFTR in 98 patients of whom 34 had acute pancreatitis (20 of biliary origin, 14 alcoholic), 46 had chronic pancreatitis (34 of alcoholic origin, one biliary, one autoimmune, 10 idiopathic) and 18 had pancreatic cancer." (PMID 20049222, 2009). "As commercial genetic testing for extended CFTR mutation analysis is now available, it is important to suspect a CFTR mutation in a patient with idiopathic chronic pancreatitis." (PMID 18501000, 2008). "In 1998, Sharer and colleagues and Cohn and colleagues were able to show an association of CFTR mutations with chronic pancreatitis." (PMID 17204147, 2007). "Some authors state that compound heterozygous CFTR carriers have a distinct elevated risk for the development of chronic pancreatitis, which is even higher when an additional SPINK1 mutation is present." (PMID 17204147, 2007).